RUNX1 (RUNX family transcription factor 1)
Diseases named in the same sentence as RUNX1 in open-access papers (continued):
Sharing a sentence is not in itself a finding about the gene and the disease.
lymphoma (21 papers, 2008 to 2026). A malignant (clonal) proliferation of B- lymphocytes or T- lymphocytes which involves the lymph nodes, bone marrow and/or extranodal sites. "Genes related to B cell signaling in B cells and genes correlated with a predisposition to lymphoma development, such as runt-related transcription factor 1 (RUNX1), are also observed to be hypomethylated." (PMID 34968227, 2019). "Our studies in lymphoma cells partially recapitulate these findings, and indicate a causal chain in which down‐regulation of Runx1 is proximal to the other changes and reversed by ectopic expression." (PMID 27869314, 2017). "While the cell lines derived from these lymphomas almost uniformly retained the functional active Runx1 allele on initial establishment in culture, they were able to survive excision of both wild-type alleles after treatment with IFNβ in vitro." (PMID 27056890, 2016). "The next-generation sequencing performed on the sample confirms that the predominant T-cell clones in this lymphoma contained CAR-T cell fusion mRNA, with potential driver mutations found in TET2, BRAF (V600E), PPM1D, ATM, and RUNX1." (PMID 41509667, 2026). "In CRISPR perturbation and RNAi cell viability screens (DepMap portal), RUNX1 was identified as a strongly selective/high-dependency gene, especially in B-lymphoblastic leukemia/lymphoma cell lines." (PMID 40646133, 2025). "The expression levels of MYCT1 and RUNX1 mRNA in the bone marrow of 12 lymphoma patients with bone marrow infiltration were detected by qPCR." (PMID 38172714, 2024). "The results showed that compared with the normal bone marrow control group, the mRNA expression levels of MYCT1 and RUNX1 in the bone marrow of lymphoma patients were significantly lower and higher, respectively." (PMID 38172714, 2024). "The results showed that compared with the reactive lymphadenitis control group, the mRNA expression levels of MYCT1 and RUNX1 in lymphoma paraffin-embedded tissues were significantly lower and higher, respectively." (PMID 38172714, 2024). "The RUNX1 gene can also be used as a target for mouse leukemia virus (MLV) insertion mutation and lymphoma transcription activation." (PMID 38172714, 2024). "MYCT1 and RUNX1 site-specific FISH probes were used to detect the copy number of MYCT1 and RUNX1 DNA in bone marrow samples of 78 patients with malignant lymphoma with abnormal karyotypes." (PMID 38172714, 2024).
lymphoma (continued). "Meanwhile, deletion of the MYCT1 locus and amplification of the RUNX1 locus occurred in lymphoma cell karyotypes, suggesting that MYCT1 and RUNX1 have opposite roles in lymphoma." (PMID 38172714, 2024). "The expression levels of MYCT1 and RUNX1 mRNA in paraffin-embedded tissues of 27 cases of lymphoma were detected by qPCR." (PMID 38172714, 2024). "Runx1 and Myc are upregulated in LP mouse lymphomas, while heterozygous deletions of Runx1 (LP; Runx1fl/+ mice) or Myc (LP; Mycfl/+ mice) prolong the lifespan of these mice and suppresses lymphoma development." (PMID 37190031, 2023). "Our results demonstrate a consistent role for Runx1 in control of sphingolipid metabolism in lymphomas as well as in normal development." (PMID 27869314, 2017). "We find that ectopic expression of Runx1 in lymphoma cells consistently perturbs the sphingolipid rheostat, whereas an essential physiological role for Runx1 is revealed by reduced S1P levels in normal spleen after partial Cre‐mediated excision." (PMID 27869314, 2017). "Primary lymphoma cells from Eμ-Myc mice show evidence of addiction to Runx1 in vivo, but become permissive for deletion in vitro." (PMID 27056890, 2016). "The present study shows that basal expression of the normal Runx1 gene is vital for maintenance of primary Myc-driven lymphoma in vivo and that this dependence is stronger than in normal lymphoid cells, providing evidence of oncogene addiction in vivo." (PMID 27056890, 2016). "Common targets in the Eμ-Myc lymphoma model include Runx1 and Runx3, while all three members of the Runx family were identified as activation targets in CD2-MYC T-cell lymphomas." (PMID 27056890, 2016). "In this study we tested the effects of ablating the endogenous Runx1 gene in the well-characterised Eμ-Myc lymphoma model system where ectopic expression of Runx1 is known to drive lymphomagenesis." (PMID 27056890, 2016). "Nor did we note any obvious change in cell size or morphology in Runx1-excised Eμ-Myc lymphoma cell lines." (PMID 27056890, 2016). "Among 27 patients with lymphoma, 19 cases were RUNX1 positive, with a positive rate of 70%." (PMID 38172714, 2024). "Moreover, we also found that MYCT1 and RUNX1 were downregulated and upregulated in lymphoma, respectively." (PMID 38172714, 2024). "MYCT1 negatively correlated with RUNX1 in lymphoma tissues of the patients." (PMID 38172714, 2024). "Moreover, we show that Runx1 regulates glucocorticoid sensitivity in lymphoma cells and identify an established direct target gene, Sgpp1, as an integrator of sphingolipid metabolism and responses to glucocorticoids." (PMID 27869314, 2017). "The unexpected survival of Eμ-Myc lymphoma cell lines after Runx1 excision in vitro led us to consider whether Runx1 is required for lymphoma re-establishment in vivo." (PMID 27056890, 2016). "These mice were further crossed to generate Mx1Cre/Runx1fl/fl cohorts in which we could examine the ability of lymphoma cells to survive deletion of the endogenous Runx1 gene." (PMID 27056890, 2016). "The Runx1 gene expression signature we observed in Eμ-Myc lymphoma cells was significantly enriched for regulators of lymphocyte proliferation, survival and differentiation, with changes consistent with the observed growth advantage and chemo-resistance associated with intact Runx1 expression." (PMID 27056890, 2016).
lymphoma (continued). "Notably, some splenic lymphomas appeared to consist of exclusively Runx1null cells, again indicating attenuation of Runx1-dependency compared to primary lymphomas." (PMID 27056890, 2016). "Moreover, the increased sensitivity of Runx1-deleted cells to components of standard chemotherapeutic regimens in current use for lymphoma therapy suggests that these may be combined with Runx inhibition for greater efficacy." (PMID 27056890, 2016). "Some scholars have found that combined transgenic mice, with T cells or B cells overexpressing MYC and RUNX1 genes, are easily accessible to lymphoma, suggesting that RUNX1 can accelerate MYC-induced lymphoma." (PMID 38172714, 2024). "Since MYCT1 and MAX are widely expressed in a variety of normal tissues, we speculate that MYCT1 may regulate the expression of RUNX1 at the transcriptional level through interaction with MAX, participating in the occurrence and development of lymphoma." (PMID 38172714, 2024). "In addition, the expression of AhR, CYP1A1, CYP1B1, RUNX1 and SLC7A8 was upregulated in MEPs of individuals with lymphoma, concomitant with enhanced nuclear localization of AhR." (PMID 37919525, 2023). "While the ability of Myc-driven lymphoma cells to grow in the absence of Runx1 is surprising, their impaired proliferation and increased chemo-sensitivity validates Runx1 function as a candidate target in future combination therapies." (PMID 27056890, 2016). "In lymphoma, the mechanism of RUNX1 and cell cycle regulation has not been reported." (PMID 38172714, 2024). "However, Runx1null lymphoma cells displayed growth impairment compared to Runx1 non-excised controls and were hypersensitive to DNA damaging agents and glucocorticoids." (PMID 27056890, 2016). "Moreover, the increased fragility of Myc-driven lymphoma cells lacking Runx1 indicates that targeting of Runx pathways is likely to be of therapeutic benefit in the context of Myc-driven lymphoma." (PMID 27056890, 2016).
myeloproliferative neoplasm (21 papers, 2009 to 2024). A clonal hematopoietic stem cell disorder, characterized by proliferation in the bone marrow of one or more of the myeloid (i.e., granulocytic, erythroid, megakaryocytic, and mast cell) lineages. "Most frequently, somatic mutations of RUNX1 were associated with the development of myeloproliferative neoplasm (MPN) (10.3-37.5%) and chronic myelomonocytic leukemia (CMML) (32.1-37%)." (PMID 35765406, 2022). "RUNX1 mutations are frequent in chronic myelomonocytic leukemia but rare in myeloproliferative neoplasms except at the acute phase." (PMID 20678218, 2010). "Evidence that cohesin regulates cell type-specific global gene transcriptional programs, and in particular, expression of the AML-associated transcription factor, RUNX1, could explain why cohesin mutations are so prevalent in myeloproliferative disorders." (PMID 24904756, 2014). "In EZH2-mutated patients with myelodysplastic or myeloproliferative neoplasms, the most common co-mutations were in ASXL1 (100%), NRAS, RUNX1, and STAG2 (29% each)." (PMID 33845873, 2021). "Mice with a targeted Flt3ITD mutation develop myeloproliferative neoplasms (MPN), and several other mutations (e.g. Npm1, Tet2 and Runx1 mutations) cooperate with Flt3ITD to drive AML in mice much as in humans." (PMID 27879203, 2016). "The knock-in model of RUNX1/RUNX1T1 under the control the Sca1 promoter induced a myeloproliferative disease, suggesting that targeting the “correct” stem/progenitor cell is important for the transformational potential of RUNX1/RUNX1T1." (PMID 25568664, 2014). "However, mutations which are reported to play a major role in myeloproliferative neoplasms, such as ten-eleven translocation-2 (TET2), runt-related transcription factor 1 isoform (RUNX1), janus kinase 2 (JAK2) V617F, and Soc-2 suppressor of clear homolog SHOC2 are not involved in JMML." (PMID 22162691, 2012). "Loss of RUNX3 was shown to cause a mild expansion of HSC and myeloid cells in aged mice, whereas disruption of both RUNX1 and RUNX3 in mice led to BM failure and myeloproliferative disease characterized by DNA repair defects." (PMID 35490198, 2022). "Furthermore, dysregulation of XIST, RUNX1, SON, ERG and STAT1 was observed, contributing to myeloproliferative disorders." (PMID 38474215, 2024).
B-cell acute lymphoblastic leukemia (20 papers, 2011 to 2025). A neoplasm of lymphoblasts committed to the B-cell lineage, typically composed of small to medium-sized blast cells. "For example, ETV6 (also known as TEL) are occasionally fused with RUNX1 (also known as AML1) in childhood precursor B-cell acute lymphoblastic leukemia." (PMID 21789226, 2011).
chronic myelomonocytic leukemia (20 papers, 2008 to 2024). A myelodysplastic/myeloproliferative neoplasm which is characterized by persistent monocytosis, absence of a Philadelphia chromosome and BCR/ABL fusion gene, fewer than 20 percent blasts in the bone marrow and blood, myelodysplasia, and absence of PDGFRA or PDGFRB rearrangement. "In a sequencing study seven different RUNX1 mutations in chronic myelomonocytic leukemia samples have been detected." (PMID 22720055, 2012). "In this paper, we uncover the germline status of RUNX1 variants in patients with a spectrum of MN (ICUS, CCUS, MDS, chronic myelomonocytic leukemia (CMML), and AML) and examine factors associated with germline RUNX1 variants." (PMID 40225162, 2023). "Mono- or biallelic deletions, missense, nonsense, and frameshift mutations in RUNX1 are also found in patients with de novo AML, MDS, chronic myelomonocytic leukemia, and in therapy-related MDS and AML." (PMID 22145044, 2011). "In addition, RAS pathway mutations with and without RUNX1 alterations have been reported in -7/7q- alterations in AML arising from MDS and chronic myelomonocytic leukemia with myelodysplastic features." (PMID 21078186, 2010).
B-cell precursor acute lymphoblastic leukemia (18 papers, 2011 to 2024). "Autophagy inhibition, spleen tyrosine kinase (SYK), and IGF2BP1 are potential future therapeutic targets for ETV6::RUNX1-driven B-cell precursor acute lymphoblastic leukemia due to their roles in ETV6::RUNX1 cell survival and prognosis." (PMID 38811988, 2024).
Down syndrome (18 papers, 2012 to 2026). "Altogether, these pieces of evidence point to a plausible role for RUNX1 triplication in the predisposition of individuals with Down syndrome to develop liver diseases, a topic that requires future elucidation." (PMID 37670378, 2023). "Hence, an extra copy of RUNX1 has been proposed to play relevant roles in some of the many phenotypic alterations associated with Down syndrome (DS)." (PMID 37670378, 2023). "Hence, RUNX1 overexpression was initially proposed as a critical player on Down syndrome-associated leukemogenesis." (PMID 37670378, 2023). "In conclusion, triplication of RUNX1 could be associated with pathological and regenerative states of the muscle, a tissue largely affected in the Down syndrome population." (PMID 37670378, 2023). "Runx1 is a transcription factor that is on chromosome 21, and Down’s syndrome patients show an increased dosage of Runx1 (trisomy 21) and have an increased risk of developing acute megakaryoblastic leukemia." (PMID 38721526, 2024). "Since RUNX1a is not expressed in rodents, interpretation of experiments on RUNX1 functions from mouse models of Down syndrome and their extrapolation to humans should be done with great caution." (PMID 37670378, 2023). "Even less is understood about the consequences on these tissues of RUNX1 gene dosage alterations in the context of Down syndrome." (PMID 37670378, 2023). "In Down syndrome, individuals carry 3 copies of chromosome 21, which results in a 1.5 fold gene dosage increase for all genes on this chromosome, including AML1/RUNX1." (PMID 30046390, 2018). "Overall, RUNX1 is required for the proper development of cardiovascular tissues and its expression correlates with disease in the adult heart; therefore, it is somewhat unexpected that RUNX1 gene triplication has not been widely associated to Down syndrome-related congenital heart disease." (PMID 37670378, 2023). "Significant factors such as ETV6 RUNX1 fusion status, karyotype, MRD day 29, Down syndrome, and DNA index were applied to construct a prognostic nomogram." (PMID 33014835, 2020). "Surprisingly, the potential implications of RUNX1 triplication or changes in its alternative splicing on bone/cartilage homeostasis in the context of Down syndrome have not been reported." (PMID 37670378, 2023). "In summary, because mouse models of Down syndrome lack the RUNX1a isoform, which may be critical to T21-associated leukemogenesis, they may not be the best system to study RUNX1 function in Down syndrome." (PMID 37670378, 2023).
T-cell acute lymphoblastic leukemia (18 papers, 2013 to 2025). Acute lymphoblastic leukemia of T-cell origin. "While loss-of-function mutations suggest a tumor suppressor role for RUNX1, RUNX1 was reported to reinforce the TAL1-driven oncogenic program in T-cell acute lymphoblastic leukemia." (PMID 36766749, 2023). "Also, our patient suffered from T-cell ALL, the rarer lineage but typical for germline RUNX1 mutation-linked lymphoblastic leukemia." (PMID 35739278, 2022). "RUNX1 has an oncogenic role in T-cell acute lymphoblastic leukemia by altering Myb and Myc enhancer activity." (PMID 40990016, 2025). "Germline predisposition, such as those associated with mutations in hematopoietic transcription factors RUNX1, ANKRD26, GATA2, and ETV6, can present with different types of hematopoietic malignancies, including MDS, AML, T-cell ALL, B-cell ALL, and myeloproliferative neoplasms (MPNs)." (PMID 35356204, 2022). "Therefore, we examined active enhancers and ‘super-enhancers’ given that the RUNX1 super-enhancer was pinpointed as a key target for THZ1 in T cell acute leukemia." (PMID 30805632, 2019). "RUNX1 and other hematopoietic TFs, TAL1/SCL, GATA2, PU.1, LMO2 and LDB1 bind at RUNX1-SE, which is observed in normal HSCs and T-cell acute lymphoblastic leukemia cells, regulate HSCs differentiation and development." (PMID 39090713, 2024).
anemia (17 papers, 2015 to 2025). A reduction in the number of red blood cells, the amount of hemoglobin, and/or the volume of packed red blood cells. "Given the emerging role of RUNX1 as a central regulator of osteogenesis, we suggest that the RUNX1 variant identified in this patient with a normochromic normocytic anemia and severe osteoporosis is potentially pathogenic." (PMID 37701147, 2023). "A young man with a normochromic normocytic anaemia, severe osteoporosis and deranged bone microarchitecture resulting in multiple fractures associated with a potentially pathogenic germline variant in the runt‐related transcription factor 1 (RUNX1) gene." (PMID 37701147, 2023). "The RUNX1 mutation was associated with worse OS and a higher AML transformation rate, while the co‐occurrence of SF3B1 with EZH2 may be associated with more severe anemia and transfusion dependency." (PMID 40342275, 2025).